IRF4 (interferon regulatory factor 4)
Diseases named in the same sentence as IRF4 in open-access papers (continued):
Sharing a sentence is not in itself a finding about the gene and the disease.
myeloma (continued). "The backbone myeloma drug lenalidomide (Len) down regulates IRF4 indirectly because it lies downstream of cereblon (CRBN), the primary target of Len, in the CRBN-IKFZ1/3-IRF4-MYC pathway." (PMID 31139207, 2019). "In line with this, combination of AI-10-104 and lenalidomide downregulated the myeloma oncogenes MYC and IRF4." (PMID 30760870, 2019). "They found that SEs assist the high level transcription of genes [e.g., MYC, IRF4 (interferon regulatory factor 4), XBP1 (X-box binding protein 1), CCND2 (Cyclin D2)] that are deregulated in multiple myeloma cells." (PMID 31824865, 2019). "Downregulation of IKZF1/3 was demonstrated to induce downregulation of IRF4 and MYC5–7, two important proteins for myeloma proliferation and survival." (PMID 30741931, 2019). "One possible explanation is that IRF4 targets already were up-regulated in transformed cells, such as MYC and its targets, which was a primary target of IRF4 in myeloma cells." (PMID 31666930, 2019). "DEPTOR knockdown in H929 and MM1S cell lines induced dedifferentiation of myeloma cells, as demonstrated by the upregulation of PAX5 and BCL6, the downregulation of IRF4, and a clear reduction in cell size and endoplasmic reticulum mass." (PMID 28420429, 2017). "We first demonstrated by qRT-PCR that IRF4 mRNA was suppressed in a dose-dependent manner by CBP/EP300 bromodomain inhibition in both LP-1 and another multiple myeloma cell line, OPM2." (PMID 26731516, 2016). "Our data suggest that CBP/EP300 bromodomain inhibition exerts its anti-myeloma effects in a mechanism distinct from BET inhibition via the direct transcriptional inhibition of IRF4 and the downstream suppression of IRF4 target genes such as MYC." (PMID 26731516, 2016). "Immunomodulatory drugs (IMiDs) thalidomide, lenalidomide (Len) and pomalidomide trigger anti-tumor activities in multiple myeloma (MM) by targetting cereblon and thereby impacting IZF1/3, c-Myc and IRF4." (PMID 25978432, 2015). "Importantly, among the upregulated genes, there were several genes encoding established pro-survival and anti-apoptotic factors in myeloma, including MYC, IRF4, NFKB1/2, BCL2, and BCL2L1." (PMID 38911853, 2024). "Accordingly, myeloma patient samples were shown to present a significantly higher expression of both MYC and IRF4 mRNA as compared to the normal plasma cells, thus further suggesting the existence of a positive correlation between IRF4 and MYC expression levels in MM." (PMID 39482742, 2024). "In addition to the induction of oxidative stress, this compound was reported to downregulate the expression of IRF-4, Sp-1, and the IKZF-1-IRF4-MYC axis, key factors for myeloma cell growth and survival, in MM cells." (PMID 38510655, 2024). "Previous research identified IRF4 as a poor prognostic biomarker in DLBCL and multiple myeloma." (PMID 36611989, 2023). "IRF4 is also a key regulator of multiple myeloma and directly activates MYC in myeloma cells." (PMID 37198323, 2023). "Through a multi-layer -omics approach, c-MAF was suggested to interact with IRF4 in normal and myeloma plasma cells although no experimental data supported this idea." (PMID 35359922, 2022). "Conversely, more mature CD138+IRF4+ cells were rare in WM relative to MZL and myeloma." (PMID 36494694, 2022). "ChIP-seq assays showed that acetylation of H3K27 at cell cycle/mitochondrial gene promoters and super-enhancers of genes relevant for multiple myeloma biology (c-MYC, BCL-XL, CCND2, IRF4, MCL1, PIM1, PRDM1, and XBP1) was mildly increased in HDAC3 knockdown cells compared with nonsilencing cells." (PMID 36846090, 2022). "The highly characteristic amplification of IRF4 (6p25.3) has not yet been reported in MM at a higher frequency, although myeloma cells are functionally addicted to IRF4 signaling and translocations involving 6p25.3 have been described." (PMID 34465776, 2021).
myeloma (continued). "A high level of myeloma cell line dependency to MEF2C in the DepMap CRISPR/Cas9 screen, highlights an important role of this TF in the biology of MM, least because of its inferred role in activating transcription of TF such as IRF4, XBP1 and PRDM1." (PMID 34521827, 2021). "Although deletion of Cereblon (CRBN), a target of iMiDs linked with interferon regulatory factor 4 (IRF4), has been associated with iMiD resistance in myeloma, the mechanism of iMiD resistance in PCNSL has not yet been clarified." (PMID 33957995, 2021). "IRF4 sustains the expression of MYC, another important myeloma oncogene." (PMID 34834536, 2021). "In contrast with lymphomas, Leukocyte Antigen (LCA), multiple myeloma 1/interferon regulatory factor 4, and k and l light chains are negative in PCs." (PMID 31205468, 2019). "Moreover, JQ1 increased the expression of MICA in multiple myeloma, since the downregulation of c-MYC leads to up-modulation of miR-125-5p and the consequent downregulation of its target gene IRF4, known as transcription repressor of MICA." (PMID 31040907, 2019). "IRF4 is also of interest from the therapeutic angle since it constitutes a “unifying Achilles heel” in myeloma, regardless of the molecular subtypes." (PMID 31139207, 2019). "Finally, IRF4 has been described as an oncogene in HTLV1-positive T-cell leukemia and in multiple myeloma." (PMID 28977998, 2017). "Of note, PU.1 expression is not uniform across primary myelomas or myeloma cell lines, suggesting the potential for significant variation in transcriptional input from IRF4 in plasma cell malignancies, which will be important to explore in future." (PMID 24875472, 2014). "This is of particular interest since ABC-DLBCL and myeloma show non-oncogenic addiction to IRF4 function." (PMID 23424639, 2013). "Using 10-E-09 as control we assessed 124 small molecules pre-selected from a library of 5120 diverse chemical compounds by their selective growth inhibitory effect on KMS-12-PE myeloma cells compared to IRF4 negative fibroblasts." (PMID 22984542, 2012). "Their growth inhibitory actions on myeloma cells compared to IRF4 negative leukemia cells appeared equally selective as with 10-E-09." (PMID 22984542, 2012). "Because transcription factors are extremely difficult to target with small inhibitors, we prevented IRF4 transcription with an IRF4‐selective ASO that could be directly delivered into cells through free uptake and has shown efficacy in cancers such as multiple myeloma." (PMID 40356256, 2025). "Left panel: In multiple myeloma (MM), IKZF1/3 binds to the canonical IKZF‐binding motif CTTCC in a complex with c‐FOS/c‐JUN to activate the transcription of genes involved in the growth and survival of MM cells such as interferon regulatory factor 4 (IRF4) and SLAMF7." (PMID 37581569, 2023). "The proliferation and survival of MM are dependent on the activity of CBP/p300, where CBP/p300 inhibition could lead to the direct suppression of IRF4 expression and concomitantly, IRF4 suppress the oncogenic transcription factor c-MYC, thus providing anti-myeloma effects." (PMID 36359286, 2022). "The fact that two of the identified RIDD targets, IRF4 and IKZF1, are targeted by IMiDs, made us hypothesize that the combination of these drugs with ER-stress inducers (that also lowered IRF4 and IKZF1 levels) could exert a synergistic anti-myeloma effect." (PMID 35361260, 2022). "In the transcriptional study, we found that IRF4, an interferon regulatory factor and B-cell specific transcription factor, is a prognostic factor in multiple myeloma independent of patient age, ISS disease stage, levels of lactate dehydrogenase, and high risk factors." (PMID 27223072, 2016). "To better understand the events downstream of IRF4 suppression that are important for reducing proliferation and viability following CBP/EP300 bromodomain inhibition, we reduced the expression of IRF4 in a panel of multiple myeloma cell lines through shRNA transduction." (PMID 26731516, 2016).
myeloma (continued). "CBP/EP300 bromodomain inhibition thus targets the IRF4/MYC network, which is critical for multiple myeloma cells independent of the upstream oncogenic signal." (PMID 26731516, 2016). "This suggests that IRF4 is essential for the proliferation of Tax-negative ATLL cells and also suggests that lenalidomide suppression of ATLL cells is mediated by more than one mechanism, as has been described in multiple myeloma." (PMID 32859220, 2020). "While BET proteins are known to similarly target MYC in multiple myeloma, a comparison of CBP/EP300 and BET bromodomain inhibition demonstrated that these modalities target the IRF4-MYC network at different nodes, with BET inhibition having no impact on IRF4 at the doses and timepoints examined." (PMID 26731516, 2016).
lymphoma (60 papers, 2010 to 2025). A malignant (clonal) proliferation of B- lymphocytes or T- lymphocytes which involves the lymph nodes, bone marrow and/or extranodal sites. "It has been indicated that LBCL, IRF4+ is a peculiar lymphoma type associated with relatively favorable prognosis." (PMID 37081786, 2023). "Here, the authors describe a recurrent mutation within TF IRF4 in human lymphomas and they show how it causes a complex switch in TF specificity and functionality." (PMID 37935654, 2023). "Adult T-cell leukemia-lymphoma was specifically associated with signature 17, which was found to correlate with the IRF4 K59R mutation that is exclusive to Adult T-cell leukemia-lymphoma." (PMID 33597573, 2021). "Using high throughput expression profiling, we have previously identified LIMD1 as a common marker associated with the oncogenic transcription factor IRF4 in EBV-related lymphomas and other hematological malignancies." (PMID 29464072, 2018). "Results show that IRF4 is overexpressed in melanoma, in addition to previously reported myeoloma, lymphoma, and leukemia, and that IRF4 is associated with a unique gene expression pattern in each of these settings." (PMID 25207815, 2014). "IRF4/Mum1 is expressed in a relatively large number of malignant lymphoma and reported to be associated with good prognosis for B-cell chronic lymphocytic leukemia (B-CLL)." (PMID 23342264, 2012). "IRF4 is involved in the differentiation and maturation of B-cells, plasma cells, as well as memory T-cells, and hence, most clinical trials targeting this molecule are associated with lymphomas or plasma cell neoplasms." (PMID 33008022, 2020). "However, all lymphomas harboring mutations in miR-142 showed expression of IRF4/Mum1 including those of GCB subtype by IHC." (PMID 23342264, 2012). "Here, we wanted to examine whether deficiency of IRF4 synergizes with the c-Myc oncogene to induce B cell leukemia and lymphoma." (PMID 21818355, 2011). "In contrast, the genome-wide and DNA-based nature of Hi-C allows it to detect these types of genomic rearrangements, as exemplified in a recent case study where Arima Genomics’ Hi-C detected an IGH::IRF4 rearrangement in a lymphoma specimen." (PMID 39272793, 2024). "It has been estimated that in the pediatric population, around 20% of morphologically FL (grade 3) and DLBCL harbor an IRF4 chromosomal translocation but represent only 1–2% of all lymphomas in children and adolescents." (PMID 37555980, 2023). "Although this lymphoma is more frequently observed in children and young adults, cases in adults share the GCB-type, IRF4 mutations, and frequent coexpression of CD10, BCL6, and MUM1." (PMID 36810796, 2023). "Although IRF4 rearrangement is a defining feature of this special type of lymphoma with relatively favorable prognosis, it should be noted such a molecular alteration is not specific for the entity." (PMID 37081786, 2023). "Mechanistically, BOB.1/OBF.1 is repressing IRF4 thereby driving GC-derived lymphoma cell proliferation." (PMID 36817488, 2023). "Interferon regulatory factor 4 (IRF4, also known as MUM1) has been implicated in immune cell development and lymphoma." (PMID 35091544, 2022). "All mice with deficiencies of IRF-4 and IRF-8 finally developed B lymphoblastic leukemia/lymphoma at the age of 25 weeks, and then died." (PMID 35211408, 2022). "Here, we establish the IRF4-driven lymphoma animal model demonstrating the emergence of highly-invasive tumors that infiltrate multiple organs." (PMID 35504924, 2022). "Our GEO high throughput profiling has revealed that LIMD1 is associated with IRF4 expression in B-cell lymphomas, including EBV-associated lymphomas and DLBC." (PMID 33869018, 2021). "The IRF4-positive lymphomas mostly presented as limited disease in the head and neck region, especially in Waldeyer’s ring, and were associated with better prognosis." (PMID 32349466, 2020).
lymphoma (continued). "Our previous study has shown that LIMD1 and IRF4 expression levels positively correlate in different hematological malignancies, including EBV-associated lymphomas." (PMID 29464072, 2018). "We found that BCL2 and IRF4 are highly expressed in both Δ3C virus-infected, and WT virus-infected lymphomas, even though EBNA3C stabilizes IRF4 protein in vitro." (PMID 30125329, 2018). "As reported recently, IRF4 translocation was identified as a primary molecular alteration in a subset of GCB-derived lymphomas." (PMID 28086220, 2017). "In conclusion, the data presented here define the relationship of IRF4 to its endogenous partners in ABC-DLBCL cell lines identifying BATF as a principle IRF4 partner in addition to SPIB in these models of lymphoma." (PMID 24875472, 2014). "Additionally, lymphoma cells demonstrate minimal staining for interferon regulatory factor-4 (IRF4)/multiple myeloma oncogene-1 (MUM1), with nuclear expression being present in less than 30% of cells." (PMID 40227781, 2025). "While MUM1 (known as interferon regulatory factor-4/IRF4) aids lymphoma subtyping, its role in systemic ALCL remains unclear." (PMID 40635103, 2025). "Large B-cell lymphoma (LBCL) with interferon regulatory factor 4 (IRF4) rearrangement (LBCL-IRF4r) is a rare type of lymphoma with an overall favorable prognosis, and has been included as a distinct entity in the 2022 revision of the World Health Organization Classification of Lymphoid Neoplasms." (PMID 40486473, 2025). "Additionally, the absence of chromosomal rearrangements commonly associated with aggressive lymphomas, such as BCL2, BCL6, and IRF4, further supported the diagnosis." (PMID 39840177, 2024). "BCL2 and IRF4 were significantly more expressed in OPN-deficient than -competent Faslpr/lpr CD19 + cells, further supporting the histopathological assessment of high-grade ABC-DLBCL lymphomas." (PMID 36503430, 2022). "In conclusion, we established an IRF4-driven zebrafish lymphoma model." (PMID 35504924, 2022). "The lymphoma type-specific protein landscape of splenic CD19 + B cells of SLE-prone mice was analyzed by western blot for the expression of BCL2, that together with c-MYC defines the class of “double expressor” lymphomas, and for IRF4, an additional marker belonging to the ABC-DLBCL signature." (PMID 36503430, 2022). "One study showed that a high level of IRF4 was expressed in LMP1-KO EBV-induced lymphoma." (PMID 28738086, 2017). "Of note, CFLAR is also downregulated by shIRF4 in JiJoye cells (1.32 fold) in the microarray results, consistent with the results from GEO bioinformatics that IRF4 correlates with CFLAR in non-Hodgkin’s lymphomas and depletion of IRF4 downregulated CFLAR protein level in EBV+ lymphoma cells." (PMID 25207815, 2014). "In addition, we have identified a panel of novel transcriptional targets including IFI27, IFI44, GBP1, CFLAR and ARHGAP18 for IRF4 in lymphomas." (PMID 25207815, 2014). "Interestingly, IRF4 is a tumor suppressor gene in lymphoma and functions as a suppressor of BCL6 transcription." (PMID 20927367, 2010). "Interestingly IRF4, a tumor suppressor gene in lymphoma and a repressor of BCL6 transcription was methylated in RL cells and down regulated in RL cells and primary FL cells." (PMID 20927367, 2010). "Other follicle center–derived lymphomas such as pediatric-type follicular lymphoma, testicular follicular lymphoma, primary cutaneous follicle center lymphoma, and large B-cell lymphoma with IRF4 rearrangement are considered distinct entities separate from conventional FL." (PMID 36394631, 2023). "The chronic stimulation by lymphoma results in T cell exhaustion driven by transcription factors such as TOX, EOMES, BATF, and IRF4, which is further affected by the immunosuppressive microenvironment and more lines of therapy." (PMID 40248244, 2025).